USP17L10 (ubiquitin specific peptidase 17 like family member 10)
Description:
Deubiquitinating enzyme that removes conjugated ubiquitin from specific proteins to regulate different cellular processes that may include cell proliferation, progression through the cell cycle, apoptosis, cell migration, and the cellular response to viral infection.
Tractability: No criterion of Open Targets' tractability assessment is met for any kind of drug.
Gene: Protein-coding gene on chromosome 4 (9,210,657 to 9,212,249, forward strand). Ensembl gene ENSG00000231396.
Subcellular location: Nucleus; Endoplasmic reticulum
Pathways (Reactome):
Metabolism of proteins: Ub-specific processing proteases
Gene Ontology:
Molecular function: cysteine-type deubiquitinase activity
Biological process: regulation of apoptotic process; protein deubiquitination
Cellular component: endoplasmic reticulum; nucleus
Homologues: Paralogues in human: USP17L11 (97% identical), USP17L20 (97% identical), USP17L22 (97% identical), USP17L17 (97% identical), USP17L18 (97% identical), USP17L19 (97% identical), USP17L24 (97% identical), USP17L25 (97% identical), USP17L26 (97% identical), USP17L27 (97% identical), USP17L28 (97% identical), USP17L29 (97% identical), and 59 more.